TREM2 (triggering receptor expressed on myeloid cells 2)
Diseases named in the same sentence as TREM2 in open-access papers (continued):
Sharing a sentence is not in itself a finding about the gene and the disease.
tauopathy (continued). "One recent report showed that TREM2 deficiency could attenuate tauopathy, thereby resulting in apparent benefits as measured by functional or biomarker assays, whereas another showed that TREM2 deficiency exacerbated tauopathy." (PMID 30283031, 2019). "Furthermore, TREM2 deficiency was reported to attenuate tauopathy against brain atrophy." (PMID 29880032, 2018). "Mouse models with TREM2 deletion exhibit an accelerated spread of pathological tau, suggesting a potential regulatory role of TREM2 in tauopathy progression." (PMID 40864734, 2025). "Their findings suggested that in pure tauopathy, impaired microglial TREM2 signaling can decrease neuroinflammation and prevent neurodegeneration." (PMID 40940798, 2025). "Specifically, multiple studies reported inconsistent roles of TREM2 signaling in neurodegeneration of β-amyloid toxicity or tauopathy." (PMID 40459937, 2025). "Conversely, TREM2 deletion in some tauopathy mouse models has been shown to reduce microglial activation and neurodegeneration." (PMID 41331787, 2025). "Further studies are required to elucidate these differences and clarify TREM2’s role in human tauopathies." (PMID 40247363, 2025). "The role of TREM2 in tauopathies is complex and context-dependent, with its effects often influenced by the presence of Aβ pathology." (PMID 40247363, 2025). "Enhancing TREM2 expression in tauopathy models with intact TREM2 function can attenuate tau pathology and neurodegenerative phenotypes." (PMID 41168805, 2025). "At the cellular level, TREM2 modulates microglial inflammatory responses to decelerate tauopathy progression." (PMID 41168805, 2025). "In a combined tauopathy–TREM2 R47H mouse model, only female mice demonstrated enhanced spatial memory deficits, and these deficits occurred amid expansion of an IFN-responsive microglia cluster." (PMID 39421070, 2024). "Conversely, TREM2 deletion has a protective effect against tauopathy, reducing microglial activation and neurodegeneration." (PMID 37961627, 2023). "Overall, both studies support the notion that, in the context of tauopathies, microglial dysfunction due to TREM2 downregulation affects tau intracellular trafficking and degradation rather than internalization." (PMID 37371067, 2023). "Herein, we explored the effects of Ab-T1, an agonistic TREM2 monoclonal antibody on Tau uptake, phosphorylation, seeding, and spreading as well as its therapeutic efficacy in a Tauopathy model." (PMID 37296669, 2023). "The contribution of TREM2 to AD progression is complex, but one recent study shows decreased microglial synapse engulfment in a pure-tauopathy PS19 mouse model and patient AD brains, both expressing the R47H variant of TREM2." (PMID 35741071, 2022). "Recent studies suggest Trem2 deletion (Trem2 KO) can aggravate tau hyperphosphorylation and enhance morphological activation phenotypes in mouse models of tauopathy." (PMID 36056435, 2022). "By 9 months, PS19/TREM2 R47H mice showed significantly alleviated tauopathy versus PS19/TREM2 CV mice." (PMID 36564824, 2022). "Little is known about the role of TREM2 in the specific context of primary tauopathies, where accumulation of pathological tau species is the main driver of cell death." (PMID 33255694, 2020). "This is in line with a recent study that linked the decrease in synaptic damage and vulnerability in a humanized Trem2*R47H tauopathy mouse model to reduced C1q expression." (PMID 33172468, 2020). "In contrast to our findings, a study of human R47H TREM2 expressed in a mouse tauopathy revealed striking attenuation of microgliosis and reduced phagocytosis of synaptic elements by microglia." (PMID 33198789, 2020). "Three recent studies tackled this problem by crossing TREM2 knockout mice with two different murine models of tauopathies." (PMID 30572908, 2018). "These pure tauopathy mouse models suggest a complex relationship between TREM2 and Tau pathology, which requires further research." (PMID 30572908, 2018).
tauopathy (continued). "These unexpected results suggest that TREM2 promotes neuroinflammation and neurodegeneration in the context of tauopathy." (PMID 30572908, 2018). "In pure-tauopathy mouse models, the relationship between TREM2 and tau pathology is complex." (PMID 40940798, 2025). "This protective effect of TREM2 loss is linked to decreased microgliosis and neuroinflammation, suggesting that TREM2-driven microglial activation may exacerbate neurodegeneration in certain tauopathies." (PMID 40247363, 2025). "Notably, TREM2 KO models exhibit robust neuroprotection in tauopathies, achieving reduced microglial overactivation, alleviation of neuroinflammation, and inhibition of neurodegeneration compared to wild type." (PMID 41168805, 2025). "TREM2 signaling has also been investigated in the context of tauopathy." (PMID 39219300, 2025). "These discrepancies are likely driven by differences in the disease models and may also reflect sex-dependent effects, underscoring the complexity of studying TREM2 R47H in tauopathies." (PMID 40247363, 2025). "However, in the case of tauopathy, the consequences of TREM2 KO are inconsistent, showing either a detrimental or protective effect depending on the specific tauopathy model used." (PMID 37887017, 2023). "Impaired TREM2 signaling reduces microglia-mediated neurodegeneration in tauopathies." (PMID 38020891, 2023). "The data presented here suggest that TREM2 deletion may be beneficial in diminishing tau propagation in a pure tauopathy setting." (PMID 37371067, 2023). "The TREM2-APOE axis has also been investigated in tauopathy and demyelination." (PMID 36564824, 2022). "Importantly, results presented here implicate a protective role for Trem2 early in tau pathogenesis and dispersion where early intervention could potentially stem or delay global effects of tau-associated degeneration in AD and potentially other related tauopathy disorders." (PMID 36056435, 2022). "Opposing roles for TREM2 have been reported in mouse models of pure tauopathies." (PMID 36564824, 2022). "Interestingly, Trem2+/+, Trem2+/-, Trem2−/− mice showed comparable changes in tau pathology in a 17-month-old pure tauopathy model." (PMID 36564824, 2022). "Given the heightened AD risk posed by rare variants of the microglial triggering receptor expressed on myeloid cells 2 (TREM2), we will focus on the studies addressing the impact of this receptor on microglia responses to amyloid plaques, tauopathy and demyelination pathologies in mouse and human." (PMID 36564824, 2022). "In contrast, opposing roles of TREM2 on tauopathy models have been reported." (PMID 36389767, 2022). "A recent report, however, highlights that the variant p.R47H seems to attenuate neurodegeneration in the PS19 model of tauopathy, and a positive modulation of the Trem2 function might lead to increase microgliosis and damage in advanced stages of tauopathy." (PMID 33823896, 2021). "Similarly, studies in pure tauopathy mice (i.e. P301S) have shown that TREM2 overexpression ameliorates tau hyperphosphorylation, neurodegeneration and cognitive decline, by suppressing neuroinflammation induced tau kinases." (PMID 33032659, 2020). "Of note, these studies were conducted in different tauopathy mouse models and the mice were of different ages, which may suggest an age-dependent effect of Trem2, which has been observed when assessing the effect of Trem2 deficiency on Aβ pathology." (PMID 32973446, 2020). "Our results are in agreement with the study by Leyns and coworkers, which suggested that increased TREM2 expression may exacerbate tauopathy, as we observed increased levels of AT8 + phospho-tau in the dentate gyrus of TIA1 knockout P301S animals." (PMID 32327969, 2020). "Moreover, reduced TREM2 signaling reduces microglial conversion to a proinflammatory phagocytic state and is protective against neurodegeneration in the setting of advanced tauopathy." (PMID 33255694, 2020).
tauopathy (continued). "In summary, our findings demonstrate a critical role for TREM2 in regulating tau related CNS innate immune responses, and identifies that TREM2 signaling plays a protective role in tauopathies despite evidence that signaling plays some detrimental roles in early Aβ pathological outcomes." (PMID 29037207, 2017). "Finally, given the results of recently published findings demonstrating potent signaling capacity of the soluble cleaved TREM2 protein, it will be necessary to explore the role of TREM2 cleavage in modifying tauopathy." (PMID 29037207, 2017). "Here we address the effect of TREM2 deficiency on another cardinal aspect of neurodegeneration, intracellular neuronal aggregates of hyperphosphorylated microtubule associated protein tau (MAPT; tau), using the hTau mouse model of tauopathy." (PMID 29037207, 2017). "However, the function of TREM2 in the context of tauopathy remains a matter for debate." (PMID 32327969, 2020). "However, the role of TREM2 in AD and tauopathy are not yet fully understood." (PMID 30283031, 2019). "However, in a study investigating PS19 mice with TREM2 KO, researchers found a reduction in brain atrophy in the absence of any changes in tauopathy or a reduction of MGnD-associated markers APOE and Cst7." (PMID 29311768, 2017). "Thus, parallel studies utilizing mice and cell models harboring the AD and FTD risk mutations including the R47H, Y38C, and T66 M TREM2 mutants, in addition to cell specific floxed TREM2 models, will be critical to directly assess the role of TREM2 in modifying tauopathy." (PMID 29037207, 2017). "In contrast, MG3, prominent in tauopathy mice, exhibits elevated expression of proinflammatory DAM genes such as Apoe, Ctsb, Cd9, and Trem2." (PMID 41331787, 2025). "The vicious circle generated by activated microglia and damaged neurons based on critical molecules, including LRP1, TREM2, and PQBP1, would definitely contribute to AD and tauopathy pathologies and would be critical therapeutic targets." (PMID 34782623, 2021). "In contrast, TREM2’s role in tauopathy models without amyloid pathology, for example the PS19 and hTau models, is less well-defined, with studies producing mixed results." (PMID 40247363, 2025). "The lack of a Gal3-dependent TREM2/APOE response indicates that Gal3 affects EV dynamics and tauopathy without directly intersecting with the TREM2/APOE signaling pathways." (PMID 37988169, 2024). "Similarly, it has been shown that TREM2 downregulation affects the phenotype of GFAP-positive astrocytes in the APP/PS1 amyloid mouse model and the PS19 model of tauopathy." (PMID 37371067, 2023). "Previous studies investigating the effect of TREM2 deletion on tauopathy mouse models without the contribution of b-amyloid have focused only on tau overexpression models." (PMID 37371067, 2023). "Interestingly, the expression changes of genes such as Gfap, Csf1, Prnp, C4b and Trem2, identified with 2 m Tau hippocampi (GSE107183) have been observed at symptomatic stages in the same rTg4510 tauopathy model in other studies." (PMID 29915328, 2018). "Notably, this ventricular enlargement is absent in female APOE3-TREM2 R47H tauopathy mice, suggesting that APOE isoform differences influence the impact of TREM2 R47H on neurodegeneration." (PMID 40247363, 2025). "However, TREM2’s role in tauopathy without amyloid pathology remains ambiguous and complex, with outcomes varying based on disease context and models." (PMID 40247363, 2025). "On the other hand, work involving another model of tauopathy (P301S) suggests that mutant tau-mediated expansion of IFN-responsive microglia may not depend on Trem2 signaling in all contexts." (PMID 39421070, 2024). "All previous in vivo studies evaluating the effect of TREM2 deletion on tauopathy mouse models without the contribution of b-amyloid have been conducted in tau overexpression models; thus, the effect of TREM2 ablation on tau propagation remains unclear." (PMID 37371067, 2023).
tauopathy (continued). "Pre-clinical studies exploring the effect of TREM2 in tauopathy have not been entirely conclusive." (PMID 32973446, 2020).
Parkinson disease (64 papers, 2013 to 2025). A progressive degenerative disorder of the central nervous system characterized by loss of dopamine producing neurons in the substantia nigra and the presence of Lewy bodies in the substantia nigra and locus coeruleus. "TREM2 variants were also linked with atypical Parkinsonism in multiple pathologies, including synucleinopathies in the context of multiple system atrophy." (PMID 40362170, 2025). "Cerebrospinal fluid (CSF) soluble TREM2 protein (sTREM2) is associated with the pathogenesis of Parkinson’s disease and helps predict sleep disorders in Parkinson’s disease patients." (PMID 39529898, 2024). "In a Parkinson’s disease animal model, TREM2 deficiency aggravated α-synuclein-induced neurodegeneration and neuroinflammation." (PMID 36463233, 2022). "TREM2 and its low-frequency variants are associated with the pathogenesis of neurodegenerative diseases such as AD and Parkinson’s disease." (PMID 34576031, 2021). "Various studies suggest that TREM2 and its variants contribute to the pathogenesis of AD, Parkinson’s Disease, and Amyotrophic Lateral Sclerosis risk." (PMID 31068200, 2019). "Likewise, a deficiency in TREM2 exacerbates neurodegeneration and neuroinflammation induced by α‐synuclein in an experimental Parkinson's disease study." (PMID 38649789, 2024). "In addition, the triggering receptor expressed on myeloid cell 2 (TREM2), a microglial surface receptor, is associated with microglial phenotype switching in neurological diseases such as AD, Parkinson’s disease, tauopathy, and ischemic stroke." (PMID 39861665, 2024). "Common variation in the TREM2 locus has also been associated by GWAS with C-reactive protein levels and potential associations of p.R47H with FTD, ALS and Parkinson's disease have also been reported, suggesting a potential role for TREM2 across different neurodegenerative disorders." (PMID 24794858, 2014). "VHB937, another TREM2 antibody, boosts chemotaxis and phagocytosis in vitro, while results from AD, Parkinson’s disease (PD), and multiple sclerosis mouse models show it can protect neuronal viability, reduce neuroinflammation, and mitigate astrogliosis." (PMID 40165251, 2025). "TREM-2 is encoded by the TREM2 gene on chromosome 6, and TREM2 mutations have been linked to FTD with parkinsonism, sometimes accompanied by myoclonus and alien limb syndrome." (PMID 40722695, 2025). "Agonistic antibodies and TREM2-boosting compounds are being investigated to enhance microglial resilience in diseases such as Alzheimer’s and Parkinson’s." (PMID 40260075, 2025). "In the context of Parkinson's disease, Trem2 has been shown to negatively regulate MAPK signalling and thereby alleviate neuroinflammatory activity." (PMID 39350473, 2024). "Take TREM2 for example, its expression is upregulated in multiple pathological conditions such as Parkinson’s disease, amyotrophic lateral sclerosis, stroke, traumatic brain injury, and AD, compared with normal controls." (PMID 33461566, 2021). "Patients with heterozygous missense mutations in TREM2 demonstrate increased susceptibility to chronic neurodegenerative disorders including frontotemporal dementia (FTD)-like syndrome, Parkinson’s disease (PD), and AD." (PMID 33557250, 2021). "It is noteworthy that studies have also associated some TREM2 variants with other neurodegenerative diseases such as ALS, Parkinson’s disease and frontotemporal dementia, although these observations are still somewhat controversial." (PMID 30572908, 2018). "Studies have shown that Trem2 can inhibit TLR4‐mediated NF‐κB activation in Parkinson's disease." (PMID 40205810, 2025). "TREM2 is pivotal in modulating immune responses, inflammation, and neuroprotection, positioning it as a promising therapeutic target for neurodegenerative diseases such as Alzheimer’s, Parkinson’s, and multiple sclerosis." (PMID 39758888, 2024).
Parkinson disease (continued). "Meanwhile, TREM2 may affect the occurrence of CNS (central nervous system) diseases, such as AD, Parkinson’s disease (PD), Amyotrophic lateral sclerosis (ALS), stroke, as well as traumatic brain injury." (PMID 34641490, 2021). "It has been reported that TREM-2 could inhibit neuroinflammation by negatively regulating the MAPK signaling pathways in experimental models of Parkinson's disease." (PMID 31900229, 2020). "Although rs75932628 in TREM2 was believed to be the risk for Alzheimer’s and Parkinson’s disease, this specific variant of the TREM2 gene was not identified in the disease or control groups." (PMID 32842621, 2020). "The TREM2 R47H variant has also been reported to be associated with increased risk of Parkinson’s disease by some but not all studies." (PMID 28768545, 2017). "TREM2 can interact with Transmembrane Protein 59 (TMEM59), a membrane-bound protein, to enhance autophagy, which may protect dopaminergic neurons against inflammation-associated damage in Parkinson’s disease." (PMID 40806186, 2025). "Importantly, Trem2 overexpression attenuates neuroinflammation in Parkinson’s disease." (PMID 32892753, 2020). "MiR-3473b can regulate the secretion of pro-inflammatory mediators by targeting TREM2/ULK1 expression, thereby modulating the role of autophagy in the pathogenesis of Parkinson’s disease (PD) inflammation." (PMID 39239635, 2024). "In the NHP CSF, 983 proteins were identified by at least two unique peptides, including proteins with key roles in neurological diseases, such as APP, TREM2 and ApoE in AD, DJ-1/PARK7 in Parkinson’s disease and the prion protein in prion diseases." (PMID 36810097, 2023). "TREM2 has gained attention due to its involvement in various neurodegenerative diseases, including AD, multiple sclerosis, amyotrophic lateral sclerosis (ALS), and Parkinson’s disease (PD)." (PMID 40507855, 2025). "Another group reported that CSF TREM2 concentrations were elevated in Parkinson's disease subgroups with a positive tau CSF biomarker signature, but not in Parkinson's disease subgroups with a positive CSF amyloid-β signature." (PMID 39666067, 2024). "Medical history revealed that none of the TREM2 p.R47H carriers were experiencing features of parkinsonism, hallucinations or delusions." (PMID 37990275, 2023). "Additionally, the miR-3473b targets the triggering receptor expressed on myeloid cells 2 (TREM2) and Unc-51 like autophagy activating kinase 1 (ULK1) to regulate the inflammatory response, such as the secretion of TNF-α and IL-1β, in Parkinson's disease." (PMID 36572876, 2022).